HYAL1 (hyaluronidase 1)
Diseases named in the same sentence as HYAL1 in open-access papers (continued):
Sharing a sentence is not in itself a finding about the gene and the disease.
serous ovarian cancer (3 papers, 2009 to 2022). "Nevertheless, another group found significantly lower levels of HYAL1 in serous ovarian cancer cells." (PMID 35767191, 2022). "Instead, the median of HYAL1 mRNA level was 69% lower in grade 3 serous ovarian cancers compared to normal ovaries (P = 0.01)." (PMID 19435493, 2009). "We examined expression of HA synthases (HAS1, HAS2, and HAS3) and hyaluronidases (HYAL1, HYAL2) in primary serous ovarian cancer cells isolated from patient ascites and CBP-resistant OV-90 cells." (PMID 31443261, 2019). "In conclusion, our results indicate for the first time that decreased expression of HYAL1 rather than increased expression of HAS1–3 correlates with the accumulation of hyaluronan in serous ovarian cancer, and provides new insight in the role of hyaluronidases in human cancer in vivo." (PMID 19435493, 2009). "We additionally showed that expression of HAS2 and HAS3 but not HAS1 or hyaluronidases HYAL1 and HYAL2 were significantly increased in chemoresistant compared to chemosensitive primary serous ovarian cancer cells." (PMID 31443261, 2019).
Stroke (3 papers, 2014 to 2025). Sudden impairment of blood flow to a part of the brain due to occlusion or rupture of an artery to the brain. "Elevated HAS1, HAS2, HYAL1, and HYAL2 were also found in post-mortem brain tissue of stroke patients, and elevated HYAL1 was observed in serum from stroke patients." (PMID 41586378, 2025). "We observed CS degradation and upregulation of HYAL1 expression in infarct lesions after onset of stroke." (PMID 33127645, 2020). "Similarly, Hyal1, Hyal2, and Has2 mRNAs become upregulated in peri-infarct tissues in a rat model of stroke induced by occlusion of the middle cerebral artery." (PMID 41586378, 2025). "As in previous studies, they observed upregulation of mRNAs of genes encoding HA synthesizing and degrading enzymes in the perilesional area at early times after stroke, and immunostaining showing increased Hyal1 in astrocytes and Has2 in astrocytes and neurons." (PMID 41586378, 2025). "Although no significant HA decrease was observed after the stroke induction, induced HYAL1, at least in part, may degrade HA after stroke onset." (PMID 33127645, 2020). "Thus, expression levels of HPSE, MMP9, and HYAL1-4 in infarct lesions at 3 and 24 h after stroke onset were investigated using Western blotting." (PMID 33127645, 2020). "It will be interesting to explore whether CEMIP is also elevated following stroke, and whether CEMIP or HYAL1 influences HA catabolism at different times following stroke." (PMID 41586378, 2025). "Because HPSE protein levels increased in vascular cells 24 h post stroke induction, the impact of glycocalyx protection on the infarct volume was next examined using low-molecular-weight heparin (LMWH: enoxaparin) as an inhibitor of HPSE and low-molecular-weight CS (pLMWCS) as an HYAL1 inhibitor." (PMID 33127645, 2020).
triple-negative breast carcinoma (3 papers, 2020 to 2022). An invasive breast carcinoma which is negative for expression of estrogen receptor (ER), progesterone receptor (PR), and human epidermal growth factor receptor 2 (HER2). "HA metabolism was further discovered by the CRISPR/Cas9-mediated knockout of HYAL1 and the shRNA-mediated down-regulation of HA-receptor CD44 in the brain-seeking triple-negative breast cancer (TNBC) cell line MDA-MB-231-BR." (PMID 36291142, 2022). "It was shown that increases in the expression of HAS2, HYAL1-2, VEGF and ABCC2 were related to worse prognosis in patients with triple-negative breast cancer (HR: 1.11, 1.14, 1.24, 1.83 and 1.09 respectively)." (PMID 33572239, 2021).
Arthritis (2 papers, 2015 to 2022). Inflammation of a joint. "Hyal-1 is of great interest, as a well-developed study is determining compounds which act as natural Hyal-1 inhibitors against diseases like arthritis and gingivitis." (PMID 36421454, 2022). "This process is mediated by increased HAS2 and decreased HYAL1 in the synovial membrane, suggesting that HA production is accelerated in arthritis." (PMID 26703073, 2015).
bladder urothelial carcinoma (2 papers, 2016 to 2021). "Furthermore, increased transcription levels of HAS1 and HYAL1 are associated with metastasizing urothelial bladder carcinoma." (PMID 27184066, 2016).
Hypertension (2 papers, 2017 to 2020). The presence of chronic increased pressure in the systemic arterial system. "After adjustment for hypertension and cardiovascular diseases HYAL-1 concentrations remained significantly higher (p = 0.005), HMW-HA levels were lower (p = 0.068) in OSA group." (PMID 33173090, 2020). "Karadag's investigation revealed that there was a significantly negative correlation between serum HYAL1 and NO level in serum of hypertension patients." (PMID 29201909, 2017).
juvenile idiopathic arthritis (2 papers, 2022 to 2024). Juvenile idiopathic arthritis (JIA) is the term used to describe a group of inflammatory articular disorders of unknown cause that begin before the age of 16 and last over 6 weeks. "Additional individuals with HYAL1-deficiency were identified through homozygosity mapping in a consanguineous Middle Eastern family presenting with familial juvenile idiopathic arthritis." (PMID 39056785, 2024).
lung squamous cell carcinomas (2 papers, 2008 to 2014). "As expected for tumour suppressor genes HYAL1 and HYAL2 were down-expressed in 15 fresh lung squamous cell carcinomas (100%) and clear cell RCC tumours (60–67%)." (PMID 18725949, 2008).
mucinous ovarian cancer (2 papers, 2011 to 2022). An invasive malignant neoplasm that arises from the ovary and is characterized by the presence of malignant epithelial cells that contain intracytoplasmic mucin and may resemble the epithelial cells of the endocervix or gastrointestinal tract. "In agreement with that, it has been reported that HYAL1 is upregulated in clear cell and mucinous ovarian cancer cells, but not in serous and endometrioid ones." (PMID 35767191, 2022).
Mucopolysaccharidoses (2 papers, 2017 to 2024). "This suggests that Hyal2 knockdown exhibits mucopolysaccharidosis-like OA change in articular cartilage similar to Hyal1 knockdown." (PMID 28765635, 2017).
mucopolysaccharidosis IX (2 papers, 2020 to 2022). "Mucopolysaccharidosis IX is a lysosomal storage disorder caused by a deficiency in HYAL1, an enzyme that degrades hyaluronic acid at acidic pH." (PMID 35710820, 2022). "In humans and mice, the complete absence of hyaluronidase 1 can cause mucopolysaccharidosis IX." (PMID 33328998, 2020).
osteoporosis (2 papers, 2022). A condition of reduced bone mass, with decreased cortical thickness and a decrease in the number and size of the trabeculae of cancellous bone (but normal chemical composition), resulting in increased fracture incidence. "Moreover, previous studies have shown that Hyal1 expression is upregulated via osteoclast formation and that Serpine1 is enriched in osteoporosis patients." (PMID 35691339, 2022). "In the future, the expression and activity of HYAL1, and the accumulation of HA, should be investigated in human bone pathological conditions, including osteoporosis and osteopetrosis, as they may represent novel pharmacological targets for medical use." (PMID 35710820, 2022).
osteosarcoma (2 papers, 2024 to 2025). A usually aggressive malignant bone-forming mesenchymal neoplasm, predominantly affecting adolescents and young adults. "In vivo, WNT5B increased osteosarcoma lung and liver metastasis and inhibited the glycosaminoglycan hyaluronic acid via upregulation of hyaluronidase 1 (HYAL1), leading to changes in the tumour microenvironment." (PMID 38689429, 2024). "Furthermore, the study identified that WNT5B can promote osteosarcoma metastasis to the lungs and liver by upregulating HYAL1, concurrently leading to the degradation of its substrate, hyaluronic acid." (PMID 41421148, 2025).
pancreatic ductal adenocarcinoma (2 papers, 2021 to 2025). An infiltrating adenocarcinoma that arises from the epithelial cells of the pancreas. "•Epigenetic Regulation: HYAL1 expression is directly regulated by epigenetic factors such as BRD2, revealing a novel layer of transcriptional control in cancers like pancreatic ductal adenocarcinoma." (PMID 41421148, 2025).
prostate adenocarcinoma (2 papers, 2013 to 2016). "Similarly, it has been reported recently that 22Rv1 human prostate adenocarcinoma cells secrete and recapture HYAL1 by endocytosis, and that this process modulates HA internalization." (PMID 27755597, 2016).
Sepsis (2 papers, 2022 to 2025). Sepsis is defined as life-threatening organ dysfunction caused by a dysregulated host response to infection. "Experimental glycocalyx protectants (e.g., sucrose octasulfate, anti-HYAL1 antibodies) mitigate AKI in sepsis models but have yet to enter clinical translation." (PMID 40718792, 2025). "Indeed, data refutes hyaluronidase-1 as a sheddase in sepsis." (PMID 35872762, 2022). "During sepsis, matrix metalloproteinase-9 (MMP-9) and hyaluronidase (HYAL1) activity upregulates, directly cleaving the glycocalyx; TNF-α and IL-1β inhibit glycocalyx synthase (e.g., EXTL3) via the TLR4/NF-κB pathway." (PMID 40718792, 2025). "While plasma hyaluronidase measurements may prove to be interesting diagnostically or functionally, it’s not clear if the plasma hyaluronidase (HYAL1), can act as a HA sheddase in either sepsis or other inflammatory diseases." (PMID 35872762, 2022).
acute kidney injury (1 paper, 2021). Sudden and sustained deterioration of the kidney function characterized by decreased glomerular filtration rate, increased serum creatinine or oliguria. "For instance, one study uncovered that shedding of HA, primarily mediated by HYAL1, contributes to the pathogenesis of various diseases, including ischemia/reperfusion (I/R), acute kidney injury (AKI), and chronic kidney disease (CKD)." (PMID 33809827, 2021).
arteriosclerosis (1 paper, 2017). A vascular disorder characterized by thickening and hardening of the walls of the arteries. "We speculated that the generation of HYAL1 quantities sped up the degradation of HA, which indirectly led to NO reduction and arteriosclerosis in subjects with vascular endothelial dysfunction." (PMID 29201909, 2017).
breast tumors (1 paper, 2016). "Integrative data mining using METABRIC dataset revealed a significant inverse correlation between ERα and HYAL1 gene expression in human breast tumors." (PMID 27764788, 2016). "The HYAL1 repression was also specific to ERα and not to ERβ, whose expression did not correlate with HYAL1 in human breast tumors." (PMID 27764788, 2016). "Our data mining analysis using the METABRIC dataset did reveal a significant negative correlation between HYAL1 and ESR1 genes in breast tumors, providing a clinical relevance to the direct down-regulation of HYAL1 by estrogen." (PMID 27764788, 2016).
cervical cancer (1 paper, 2025). A primary or metastatic malignant neoplasm involving the cervix. "Furthermore, regarding mechanistic interventions, natural polyphenols including Plumbagin, Pongapin, and Karanjin significantly downregulated HYAL1–4 expression in cervical cancer HeLa cells, with HYAL1 suppression being most prominent." (PMID 41421148, 2025).
chondrosarcoma (1 paper, 2025). A malignant cartilaginous matrix-producing mesenchymal neoplasm arising from the bone and soft tissue. "In addition to these Hyal1 and/or testicular hyaluronidase inhibitors, the panel also included ipriflavone, an isoflavone that has been suggested to influence HA metabolism in CEMIP-expressing chondrosarcoma cells." (PMID 39851529, 2025).
endometrioid tumor (1 paper, 2011). A benign, borderline, or malignant epithelial tumor of the female reproductive system characterized by the presence of glands and/or cysts lined by neoplastic cells that resemble endometrial cells. "Levels of HYAL1 mRNA are significantly elevated in clear cell and mucinous carcinomas (Mann Whitney test, P<0.05) but not in serous and endometrioid tumors." (PMID 21695196, 2011).
esophageal squamous cell carcinoma (1 paper, 2024). Esophageal squamous cell carcinoma (ESCC) is a type of esophageal carcinoma (EC) that can affect any part of the esophagus, but is usually located in the upper or middle third. "Recent studies have shown that esophageal squamous cell carcinoma (ESCC)-derived exosomes containing hyaluronidase 1 facilitate M2 macrophage polarization by targeting Aurora B kinase to activate the PI3K/AKT signaling pathway, which in turn promotes ESCC progression." (PMID 39170251, 2024).
fibrosis (1 paper, 2021). the formation of excess fibrous connective tissue in an organ or tissue in a reparative or reactive process. "However, an interaction of the D2 signaling pathway with hyaluronidase 1 and hyaluronic acid in experimental fibrosis has not been described before." (PMID 34070506, 2021).
gastric cancer (1 paper, 2022). A primary or metastatic malignant neoplasm involving the stomach. "Overexpression of miR-148a-3p can inhibit the occurrence of gastric cancer by inhibiting the hyaluronidase 1 gene and promoting cell apoptosis." (PMID 36349193, 2022).
glioma (1 paper, 2023). A benign or malignant brain and spinal cord tumor that arises from glial cells (astrocytes, oligodendrocytes, ependymal cells). "In TCGA and GEPIA databases, we found that among the 6 human hyaluronidases (HYAL1, HYAL2, HYAL3, HYAL4, HYALP1, SPAM1), only HYAL2 expression was highest in glioma." (PMID 37568202, 2023). "In the present study, our results confirmed that among the six hyaluronidases (HYAL1, HYAL2, HYAL3, HYAL4, HYALP1, SPAM1), only HYAL2 was overexpressed in glioma patients, and HYAL2 overexpression was negatively correlated with the survival time of glioma patients." (PMID 37568202, 2023).
Granuloma (1 paper, 2025). A compact, organized collection of mature mononuclear phagocytes, which may be but is not necessarily accompanied by accessory features such as necrosis. "Furthermore, we identified Flrt2, Hyal1, and Mmp13 as novel molecular markers of Plin2-expressing macrophages, which were localized to the peripheral rim regions of necrotizing granulomas." (PMID 40843005, 2025).
head and neck cancer (1 paper, 2021). A primary or metastatic malignant neoplasm affecting the head and neck. "In thirty-three TCGA transcriptomic cohorts, TGFBI was a poor indicator of seven cancer types, including head and neck cancer; HYAL1 was a protective marker for four cancer types, including kidney renal clear cell carcinoma and uveal melanoma." (PMID 34869001, 2021). "In The Cancer Genome Atlas, TGFBI was a poor marker not only for head and neck cancer but also for additional six cancer types and HYAL1 was a good indicator for four tumor cohorts, suggesting common stromal effects existing in different cancer types." (PMID 34869001, 2021).
ischemic stroke (1 paper, 2020). A stroke disorder caused by obstruction of blood flow to the brain, due to thrombotic (local blood clot formation) or embolic (due to a blood clot or other material traveling from another site) event. "Glycocalyx dysfunction, due to HPSE or MMP9, in several diseases and increased levels of HYAL1 and 2 in infarct lesions of ischemic stroke patients were reported." (PMID 33127645, 2020).
liver fibrosis (1 paper, 2022). "We assessed the expression of HYAL1 and HYAL2 in liver samples from our cohort of patients with chronic HBV infection and clinically diagnosed liver fibrosis." (PMID 35662287, 2022). "HYAL2 but not HYAL1 was upregulated in patients with advanced-stage liver fibrosis." (PMID 35662287, 2022).
mucopolysaccharidosis type 7 (1 paper, 2024). Mucopolysaccharidosis type VII (MPS VII) is a very rare lysosomal storage disease belonging to the group of mucopolysaccharidoses. "Finally, mucopolysaccharidosis type VII and type IX are caused by mutations in genes encoding the enzymes beta-glucuronidase (GUSB) and hyaluronoglucosaminidase-1 (HYAL1), respectively." (PMID 38425718, 2024).
oral cancer (1 paper, 2021). "Taken together, the prognostic values of TGFBI and HYAL1 identified from betel quid-associated oral cancer tissues were recapitulated by seven (n=2834) and four (n=1048) TCGA cancer types, respectively." (PMID 34869001, 2021). "MyCAF-TGFBI and endothelial-HYAL1 were poor and good prognosis markers, respectively, for 40 betel quid-associated oral cancer tissues." (PMID 34869001, 2021). "By incorporating disease-matched xenograft tissue and single-cell RNA-seq results, we suggested that TGFBI and HYAL1, primarily expressed by stromal CAFs and endothelial cells, respectively, could serve as robust prognostic biomarkers for oral cancer control." (PMID 34869001, 2021).
Osteopenia (1 paper, 2022). Osteopenia is a term to define bone density that is not normal but also not as low as osteoporosis. "HYAL1 affects both osteoclast and osteoblast function, most likely by controlling HA concentration in bones, and a lack of HYAL1 induces osteopenia." (PMID 35710820, 2022).
peritonitis (1 paper, 2023). Inflammation of the peritoneum (tissue that lines the abdominal wall and covers most of the organs in the abdomen). "Expression of the genes coding for HA synthases (Has1-3) and hyaluronidases (Hyal1, 3) was not significantly affected by peritonitis." (PMID 38094743, 2023).
psoriasis (1 paper, 2024). An autoimmune condition characterized by red, well-delineated plaques with silvery scales that are usually on the extensor surfaces and scalp. "Since K14/HYAL1 mice recapitulated many of the gut responses observed following skin wounding, this suggests that HA digestion is one mechanism by which skin wounding, and potentially other forms of skin inflammation including psoriasis, can communicate with the colon." (PMID 38589392, 2024).
Salmonella Infections (1 paper, 2021). Infections with bacteria of the genus SALMONELLA. "Many of these genes (e.g. Lhfpl2, Bhlhe41, Hyal1, and Tbc1d2) have previously been reported as differentially expressed in M1 vs. M2 macrophages and their downregulation likely represents M1 polarization that occurs following Salmonella infection." (PMID 34305890, 2021).
scleroderma (1 paper, 2025). Scleroderma is a rare autoimmune connective tissue disorder characterized by abnormal hardening of the skin and, sometimes, other organs. "In scleroderma, patients have normal activity levels of HYAL1 in the early stages, but HYAL1 activity decreases in the late stages." (PMID 40646377, 2025).
urinary tract infection (1 paper, 2020). "Extracts from the roots of Ononis spinosa L. (restharrow roots) are traditionally used for the treatment of patients with urinary tract infections due to its mild diuretic activity, caused by the inhibition of renal human hyaluronidase-1 by isoflavonoids." (PMID 32595508, 2020).
uveal melanoma (1 paper, 2021). A melanoma derived from melanocytes of the uveal tract. "Interestingly, kidney renal clear cell carcinoma (KIRC, n=533) and uveal melanoma (UVM, n=80) concurrently displayed TGFBI and HYAL1 as poor and good biomarkers, respectively." (PMID 34869001, 2021).